DOCK2 (dedicator of cytokinesis 2)
Diseases named in the same sentence as DOCK2 in open-access papers (continued):
Sharing a sentence is not in itself a finding about the gene and the disease.
chronic lymphocytic leukemia (7 papers, 2019 to 2025). "It has also been demonstrated that DOCK2 was abnormally elevated expressed in B‐cell lymphoma and the overexpressed DOCK2 correlated with the reduced prognosis of chronic lymphocytic leukaemia." (PMID 33259129, 2021). "It has been reported that DOCK2 gene is overexpressed in chronic lymphocytic leukemia B-cells promoting their proliferation in response to Wnt5a." (PMID 30753220, 2019). "Therefore, DOCK2 is considered to be a viable drug target for leukemia, where DOCK2 is overexpressed in chronic lymphocytic leukemia." (PMID 32322580, 2020). "Notably, DOCK2 is a potent RAC1 activator in cancers, including melanoma and chronic lymphocytic leukemia, and regulates critical processes such as lymphocyte migration, T-cell differentiation, cell-cell adhesion, and bone marrow homing of immune cells." (PMID 41034404, 2025).
leukemia (7 papers, 2019 to 2025). A malignant (clonal) hematologic disorder, involving hematopoietic stem cells and characterized by the presence of primitive or atypical myeloid or lymphoid cells in the bone marrow and the blood. "Using proximity-based biotin labeling we define the RASSF2-proximal proteome in leukemia cells and reveal association with Rac GTPase-related proteins, including an interaction with the guanine nucleotide exchange factor, DOCK2." (PMID 32029705, 2020). "Further studies revealed that reduced DOCK2 expression decreased Rac1, ERK and STAT5 activity in leukemia cells bearing FLT3-ITD mutations." (PMID 36250020, 2022). "Inhibition of proliferation and colony formation in FLT3-ITD mutant leukemia cells by reducing DOCK2 expression." (PMID 36250020, 2022). "RASSF2 was also recently revealed to interact with DOCK2, suggesting that DOCK2 may influence leukemia development via multiple pathways." (PMID 36250020, 2022). "Since Crkl enhances the migration of leukemic cells and promotes the development of leukemia, the combination of Crkl and DOCK2 may be the one of the therapeutic targets for leukemia." (PMID 36250020, 2022). "This also suggests that DOCK2 may regulate the growth of FLT3-ITD leukemia cells through both MMR and DDR molecular mechanisms." (PMID 36250020, 2022). "In T cells DOCK2 acts downstream of the T cell receptor, and recently DOCK2 was implicated in mediating signalling from the FLT3 protein tyrosine kinase and identified as a leukaemia drug target." (PMID 32651375, 2020). "We speculate that DOCK2 may play a prognostic role in leukemia by interacting with genes in these functional pathways." (PMID 31762818, 2019). "In summary, we found that Wnt5a induces ROR1 to recruit and activate DOCK2, leading to activation of ERK1/2, which appears responsible for the capacity of Wnt5a to enhance leukemia-cell proliferation." (PMID 33097837, 2021). "Combining treatment with DOCK2 knockdown and DDR inhibitors such as CHK1 inhibitor MK876, WEE1 inhibitor MK1775, and RAD51 inhibitor 1302 significantly enhanced the sensitivity of mice with FLT3-ITD mutant leukemia cells to cytarabine." (PMID 36250020, 2022). "Because the lymphocytes of healthy adults do not express ROR1, this pathway of Wnt5a-induced DOCK2 phosphorylation may be restricted to leukemia B cells." (PMID 33097837, 2021).
lymphopenia (7 papers, 2019 to 2025). Reduction in the number of lymphocytes. "Prior studies have confirmed that biallelic mutations in DOCK2 impair T-cell activation, and patients with DOCK2 deficiency have T-cell mitochondrial dysfunction and lymphopenia." (PMID 40510337, 2025). "In patients with DOCK2 mutations, similar T cell lymphopenia has been seen, along with impaired lymphocyte actin cytoskeleton polymerization." (PMID 36836791, 2023). "NGS sequencing of a group of patients with CID features associated with CD4 lymphopenia revealed DOCK2 deficiency in 3 patients and CARD11 deficiency in 3 patients." (PMID 35655284, 2022). "Given all cases with available data had low TREC levels and the arguable evidence of lymphopenia adherence to this disease, DOCK2 deficiency could be recognizable through newborn SCID screening programs." (PMID 34872585, 2021). "Therefore, more studies are required to elucidate whether lymphopenia is inherent to DOCK2 deficiency." (PMID 34872585, 2021). "Of note, the persistent lymphopenia observed in DOCK2-deficient patients could be due to the recurrent infections that occurred in these cases, which is more prominent in our patient who manifested with skeletal tuberculosis, an unusual infection that has not been previously reported." (PMID 34872585, 2021). "DOCK2 knockout mice have severe peripheral lymphopenia, due to defects in development and chemotaxis of T cells, and lymphoid follicle hypoplasia." (PMID 38366567, 2024). "DOCK2 deficiency has been well studied in uninfected mice, and our new DOCK2 mouse strains replicate these findings with absent marginal zone B cells, low numbers of NKT cells, and T-cell lymphopenia." (PMID 38366567, 2024).
viral infections (7 papers, 2019 to 2024). "In a study of five patients with biallelic mutations in DOCK2, all were found to have invasive bacterial and viral infections early in life, and in vitro studies of patient immune cells showed multiple abnormalities." (PMID 36836791, 2023). "Another pathway disrupted by DOCK2 deficiency is the formation of human interferons (IFNs), essential signaling proteins in defense against viral infections." (PMID 36836791, 2023). "Five infants with double allele mutations in DOCK2, which are accompanied by aggressive bacterial and viral infections, were identified in 2015." (PMID 36250020, 2022). "DOCK2 deficiency is a congenital immunodeficiency and a rare autosomal recessive combined immunodeficiency presenting with very early onset, severe bacterial and viral infections." (PMID 36250020, 2022). "Combined immunodeficiency due to mutations in DOCK2, an activator of Rho GTPases such as RAC1 and RAC2, lead to early‐onset invasive bacterial and viral infections, lymphopenia, and various defective T‐cell, B‐cell, and NK‐cell responses." (PMID 30565237, 2019). "However, these innate mechanisms seem unlikely to underlie a susceptibility to viral infections, nor do these articulate well with the known requirement for DOCK2 in lymphocytes." (PMID 38366567, 2024). "These include DOCK2, which is known to activate RAC1/RAC2 genes required for implantation, and TRIM25, a gene involved in innate immune response against viral infection, mediating estrogen action and whose downregulation during embryogenesis in medaka has been shown to result in apoptosis." (PMID 37789509, 2023).
Alzheimer disease (6 papers, 2014 to 2024). A progressive, neurodegenerative disease characterized by loss of function and death of nerve cells in several areas of the brain leading to loss of cognitive function such as memory and language. "Genes that were both selective for and highly expressed in the microglial cluster were Tgfbr1, Cyth4, Ikzf1, Dock2, and Inpp5d, many of which are associated with Alzheimer’s Disease (AD)." (PMID 38263132, 2024). "In Alzheimer’s disease, there is an increase in the number of Dock2-expressing microglia, a finding of pathogenic significance given that Dock2 deficiency reduces the size of β-amyloid (Aβ) plaque in cerebral cortex and hippocampus of a mouse model of AD." (PMID 25309324, 2014). "Not only that, DOCK2 may be a molecular target for controlling cardiac transplant rejection and Alzheimer’s disease (AD)." (PMID 36250020, 2022). "This is in line with our previous finding of an involvement of DOCK2 in PTSD, a gene which has also been implicated in the formation of amyloid plaques in the brain in Alzheimer’s disease, suggesting the role of genes common to both PTSD and neurodegenerative disorders." (PMID 34239411, 2021). "In addition, DOCK2 may be a molecular target for controlling heart transplant rejection and Alzheimer’s disease (AD)." (PMID 36250020, 2022). "Dedicator of cytokinesis 2 (DOCK2) is a microglia marker that regulates neuroinflammatory processes related to neurodegenerative disorders, such as Alzheimer’s disease." (PMID 35625844, 2022).
colitis (6 papers, 2016 to 2024). Inflammation of the colon. "Here, we demonstrate loss of Dock2 in a Dextran Sodium Sulphate (DSS) colitis-induced mouse model of IBD-CRC increases tumour formation." (PMID 39242821, 2024). "We also observed decreased tumourigenesis in a colitis induced Dock2 deficient tumour model following 1-L-MT treatment, outlining the importance of tryptophan metabolism in modulating colitis-induced CRC." (PMID 39242821, 2024). "DOCK2 has been shown to play a key role in fighting colitis caused by Citrobacter rodentium infection and protecting the intestine by regulating macrophage function and stabilizing the diversity of intestinal flora." (PMID 36250020, 2022). "DOCK2−/−mice have been shown to be more susceptible to colitis caused by Citrobacter infection than WT mice, as evidenced by higher mortality, weight loss, Citrobacter load, and intestinal damage." (PMID 36250020, 2022). "Our previous study showed that Dock2−/− mice were more susceptible to colitis induced by C. rodentium infection than WT mice." (PMID 34391464, 2021). "Our previous study showed that Dock2−/− mice were more susceptible to colitis induced by C. rodentium infection, which was mainly manifested by higher mortality, weight loss, C. rodentium load and intestinal damage." (PMID 34391464, 2021). "Our previous study showed that, compared to wild type (WT) mice, Dock2−/− mice were more susceptible to colitis induced by Citrobacter rodentium infection." (PMID 34391464, 2021). "Shortening of the cecum and colon – a hallmark of colitis – was more pronounced in infected Dock2−/− mice on day 14 compared with infected WT mice." (PMID 27291827, 2016). "Importantly, we found in this study that the degree of weight loss during DSS-induced colitis was comparable between Sult2b1+/+ and Sult2b1−/− mice when Dock2 was genetically deleted." (PMID 37006281, 2023). "So far, DOCK2 alleviates the onset and progression of colitis by regulating the composition of macrophages and microorganisms." (PMID 36250020, 2022). "The intestinal flora of both WT and DOCK2−/− has been found to be unable to resist Citrobacter-induced colitis after removal by antibiotics." (PMID 36250020, 2022). "In the Gpsm3−/−and Dock2−/− colitis models, the colon weight/length ratio was significantly higher than that in wild-type mice." (PMID 28892060, 2017). "Dock2—/— mice are also more sensitive to colitis as a result of Citrobacter rodentium infection." (PMID 39242821, 2024). "Then, we hypothesized that DOCK2 in immune cells is the functional target of CS during colitis because CS binds to the catalytic domain of DOCK2 and inhibits its Rac-GEF activity." (PMID 37006281, 2023). "However, the exact mechanism of DOCK2 in the defense against colitis needs to be further explored and elaborated." (PMID 36250020, 2022). "Results suggested involvement of the KDGs in both T cell and myeloid functions in colitis, with a dominant role in the myeloid compartment; the exception was Dock2−/− mice, in which the KDG was demonstrated to have a more dominate role in the T cell compartment." (PMID 28892060, 2017). "Thus, DOCK2 plays a role in early colitis by regulating macrophages." (PMID 36250020, 2022). "Although neutrophils play a key role in DSS-induced colitis and IND-induced SI ulcer formation, the gastrointestinal tract contains many subsets of immune cells other than neutrophils and they express DOCK2." (PMID 37006281, 2023). "However, the exact mechanism by which Dock2 protects host from enteric bacterial infection or colitis has not been described." (PMID 34391464, 2021). "Importantly, this was not due to IDO1 inhibition impacting on severity of colitis, confirming the tumour promoting effects of increased epithelial IDO1 activity following Dock2 deletion." (PMID 39242821, 2024).
Sepsis (6 papers, 2020 to 2025). Sepsis is defined as life-threatening organ dysfunction caused by a dysregulated host response to infection. "Our data showed that DOCK2 deficiency enhanced Th1 cell immune response and proliferative capacity in LPS-induced sepsis." (PMID 40510337, 2025). "In this study, our data revealed that DOCK2-deficient mice had reduced survival rate in LPS-induced sepsis and were more susceptible to LPS-induced sepsis, including weight loss, eye exudate formation, and histomorphologic changes of various organs." (PMID 40510337, 2025). "Given the limitations of the LPS-induced sepsis model, we performed studies in Dock2−/− mice using clinically relevant live E. coli infection and identified that DOCK2 deficiency also promoted susceptibility and Th1 response to E. coli sepsis." (PMID 40510337, 2025). "DOCK2-deficient mice were highly sensitive to LPS-induced sepsis and E. coli sepsis with increased levels of inflammatory cytokines, especially IFN-γ which were mainly due to hyperresponsive Th1 cells." (PMID 40510337, 2025). "For further confirmation, we ascertain the effect of Th1 on DOCK2-deficient mice in LPS-induced sepsis by blocking IFN-γ and depleting CD4+ T cells in vivo." (PMID 40510337, 2025). "As sepsis is closely associated with multiple-organ injury and dysfunction, we next evaluated histopathology changes in the spleen, lung, and liver of the Dock2−/− and WT mice by H&E staining." (PMID 40510337, 2025). "Ulteriorly, depletion endogenous CD4+ T cells alleviated susceptibility of LPS-induced sepsis in Dock2−/− mice." (PMID 40510337, 2025). "Furthermore, DOCK2 deficiency promoted host susceptibility to E. coli sepsis and exhibited evaluated Th1 response that is required." (PMID 40510337, 2025). "Together, these data suggest that DOCK2-deficiency lead to more susceptible to LPS-induced sepsis." (PMID 40510337, 2025). "Taken together, these data indicated that DOCK2 provides robust protection against live bacterial infection, other than LPS-induced sepsis." (PMID 40510337, 2025). "Increased serum aspartate aminotransferase (AST) also indicated more severe sepsis-induced liver injury in Dock2−/− mice." (PMID 40510337, 2025). "Ulteriorly, we verified the vital role of DOCK2-mediated Th1 cells in sepsis by neutralizing both IFN-γ and CD4 and found both of which blockade reduced the severity of sepsis in Dock2−/− mice." (PMID 40510337, 2025). "Dock2−/− mice have shown reduced animal survival after LPS-induced sepsis and exhibited much severe organ injury and more excessive Th1 immune response." (PMID 40510337, 2025). "Collectively, our study highlights DOCK2 potentially a protective target for sepsis intervention in mice." (PMID 40510337, 2025). "To explore the immune mechanisms by which Dock2−/− mice exhibited much higher level of IFN-γ in the LPS-induced sepsis, we next profiled the major potential immune cells closely associated with sepsis, including macrophages, nature killer (NK) cells, and T cells." (PMID 40510337, 2025). "Here, we explored the role of DOCK2 on Th1 immune response in mice during LPS-induced sepsis." (PMID 40510337, 2025). "Overall, these findings suggest DOCK2 as an essential, negative regulator in LPS responses that protect the host from harmful hyperresponsiveness to LPS and may provide new insight into the endotoxin-induced sepsis." (PMID 40510337, 2025). "Thus, partial dominant-negative mutations in DOCK2 (herein) and DOCK8 altering NK cell lytic function may contribute to sHLH development during excess inflammatory states such as sepsis." (PMID 36836791, 2023). "Overall, through mouse study and online patient data analysis, five genes (CD247, DOCK2, IFI35, ITK, and LCK) were reported to positively correlate with sepsis prognosis whilst only the expression of MED25 displayed a negative correlation." (PMID 37456011, 2023). "Nevertheless, the regulatory role of DOCK2 on IFN-γ–producing Th1 response in LPS-induced sepsis has not yet been elucidated." (PMID 40510337, 2025).
Sepsis (continued). "CD247, DOCK2, IFI35, ITK, LCK, and MED25 might be important targets affecting the prognosis of sepsis." (PMID 33015708, 2020). "To further explore whether DOCK2 regulates IFN-γ–producing CD4+ T cells that trigger LPS-induced sepsis or not, firstly, we detected the role of IFN-γ in DOCK2-deficient mice when they suffered from endotoxin-induced septic shock." (PMID 40510337, 2025). "Sepsis development/progression in mice could be regulated by changing the LPS amount, as an example of using different doses of LPS to set survival and death groups in the discovery of six genes (CD247, DOCK2, IFI35, ITK, LCK and MED25)." (PMID 37456011, 2023).
acute myeloid leukemia (5 papers, 2019 to 2022). Acute myeloid leukemia (AML) is a group of neoplasms arising from precursor cells committed to the myeloid cell-line differentiation. "Recent research exhibited that a high expression level of DOCK2 conferred a good prognosis of acute myeloid leukemia." (PMID 35620462, 2022). "In another study, in 85 patients with AML of unknown etiology, high expression of DOCK2 implied an excellent prognosis for acute myeloid leukemia." (PMID 36250020, 2022).
lung carcinoma (4 papers, 2016 to 2022). "In summary, DOCK2 may play an important role in the development of lung cancer, but the specific mechanism needs to be further explored in depth." (PMID 36250020, 2022). "To date, the roles of ABR, PREX1, DOCK2, and DOCK4 in lung cancer are largely unknown, and the underlying mechanisms remain to be explored." (PMID 34783629, 2021). "Therefore, the DOCK2 methylation level may serve as a new biomarker for lung cancer detecting." (PMID 36250020, 2022). "The downregulation of ABR, PREX1, DOCK2 and DOCK4 in NSCLC can be induced by promoter methylation, and their methylation profiles might be potential indicators for lung cancer screening." (PMID 34783629, 2021). "Thus, DNA hypermethylation might contribute to the downregulation of ABR, PREX1, DOCK2, and DOCK4 in NSCLC, and the methylation profiles of the four key Rho GEFs may be novel biomarkers for lung cancer screening." (PMID 34783629, 2021).